RBMS1 (RNA binding motif single stranded interacting protein 1)
Diseases named in the same sentence as RBMS1 in open-access papers (continued):
Sharing a sentence is not in itself a finding about the gene and the disease.
tumor (continued). "Since we uncovered that depleted RBMS1 reduces PD-L1 level, thereby promoting anti-tumor T-cell immunity, we chose CTLA4 blockade for the combination therapy with RBMS1 depletion in the mouse 4T1 engraftment model." (PMID 35538152, 2022). "At the same time, Dankert and collaborators have also demostrated that miR-106b can regulate endogenous RBMS1 expression in PCa cell lines and, thereby, act as a tumor suppressor gene with inhibitory effects on colony formation and cell growth." (PMID 35625981, 2022). "Strikingly, the lung lesions derived from RBMS1-OE GC cell injection showed a significantly higher average tumor burden than those derived from NC cells (P < 0.01)." (PMID 35361764, 2022). "Since we detected impaired cell growth, gap closing and colony forming after RBMS1 overexpression in LNCaP cells, these observations confirm the characteristics of NE-like PCa tumour cells, which show a diminished cell proliferation." (PMID 33093529, 2020). "The remaining three common genes (EBF3, DKFZp667I0324 and RBMS1) were all bivalent in normal tissue but lost all their histone methylation in tumor." (PMID 22011431, 2011). "Additionally, RBMS1 promotes tumor progression by regulating cell proliferation, apoptosis, and ferroptosis in tumor cells." (PMID 41315216, 2025). "RBMS1 ablation inhibits the translation of S100P and suppresses tumor metastasis." (PMID 38342601, 2024). "Furthermore, IHC staining of mice xenograft tumours demonstrated that circIDE overexpression increased the level of RBMS1 and 4HNE, while Ki67 and GPX4 expression was decreased by circIDE overexpression." (PMID 36989117, 2023). "In addition, the expression of RBMS1 was declined with tumour staging (T stage) progress and advanced clinical TNM stage." (PMID 36989117, 2023). "Interestingly, knockdown of RBMS1 significantly suppressed tumor growth in the immune competent model, suggesting the differential tumorigenicity was attributed to immune surveillance." (PMID 35538152, 2022). "RBMS1 ablation stimulated cytotoxic T cell mediated anti-tumor immunity." (PMID 35538152, 2022). "Importantly, depletion of RBMS1 significantly augmented the anti-tumor effect of B7-H3.CAR-T cells at relatively low T-cell to tumor cell ratio (1:4)." (PMID 35538152, 2022). "In this study, we revealed the importance of the KCNQ1OT1/miR-378a-3p/RBMS1 axis as a ceRNA regulation network for GC prognosis by analyzing high-throughput sequencing datasets and exploring a multigene prognostic model for tumor-related mortality estimation in GC patients." (PMID 35910231, 2022). "Depletion of RBMS1 reduced tumor size and inhibited 4T1 cell-induced tumor growth." (PMID 35538152, 2022). "Importantly, combination of RBMS1 depletion with CTLA4 immune checkpoint blockade or CAR-T treatment enhanced anti-tumor T-cell immunity both in vitro and in vivo." (PMID 35538152, 2022). "Furthermore, we analysed primary PCa tissue samples and detected a matchable strong reduction of RBMS1 mRNA in tumours compared to the corresponding healthy prostate tissue." (PMID 33093529, 2020). "We then applied NTP, an RBMS1 inhibitor, to target RBMS1, and found that NTP attenuated tumor metastasis both in vitro and in vivo studies using a mouse lung metastasis model." (PMID 38342601, 2024). "CircEXOC6B can bind with RBMS1 and HuR and elevate AKAP12 (A-kinase anchoring protein 12) expression levels, leading to inhibition of tumor metastasis in prostate cancer." (PMID 38152652, 2023). "Moreover, we analyzed tumor tissues by an IHC assay and found that RBMS1-depletion induced reduction of PD-L1 and elevated infiltration of CD8+ T cells could be reversed by re-expression of B4GALT1, resulting in increased levels of PD-L1 and Ki67, but decreased infiltration of CD8+ T cells." (PMID 35538152, 2022). "Collectively, RBMS1 ablation reduces the level of B4GALT1 to inhibit the glycosylation of PD-L1, thereby stimulating the anti-tumor T-cell immunity." (PMID 35538152, 2022).
tumor (continued). "We identified RBMS1 as a hit in the screen carried out in SUM149PT cells, but shRNA-mediated depletion of RBMS1 in vivo did not significantly affect the survival of KB1P tumor-bearing mice." (PMID 37209095, 2023). "However, the effects of circIDE were further reversed by additional GPX4 overexpression for the expression of RBMS1, Ki67, GPX4, and 4HNE in xenograft tumours." (PMID 36989117, 2023). "Then, we analysed the expression of RBMS1, GPX4, and 4HNE in mice xenograft tumours." (PMID 36989117, 2023). "Finally, we constructed a model using four genes, RBMS1, ZC3HAV1, QKI, and RBM38, to calculate the Tumor Immune Dysfunction and Exclusion (TIDE) score." (PMID 37628671, 2023). "The effector function of CD8+ T cells in the spleen and lymph nodes were comparable in mice inoculated with RBMS1-depleted or control 4T1 cells, indicating that the difference in the intratumoral CD8+ T cell effector function was due to the tumor microenvironment." (PMID 35538152, 2022). "We did not observe any significant changes in tumor growth between mice inoculated with RBMS1-depleted or control cells." (PMID 35538152, 2022). "Gains in some of the genes involved in invasive/migratory properties (MGAT5, PKP4, ITGB6), cell cycle progression and regulation of apoptosis (RBMS1), and angiogenesis (NRXN1) may be involved in tumor development and progression." (PMID 26432421, 2015). "Similarly, the results of our analysis suggest that the lncRNA, KCNQ1OT1, acts as a competitive endogenous RNA that competitively binds tumor-suppressive miR-378a-3p, resulting in increased expression of RBMS1 within tumors via the KCNQ1OT1/miR-378a-3p/RBMS1 axis." (PMID 35910231, 2022). "However, when RBMS1 is depleted, it destabilizes B4GALT1 transcript, resulting in the suppression of glycosylation and increased degradation of PD-L1, thus promoting anti-tumor T-cell immunity and sensitizing TNBC cells to anti-CTLA4 therapy." (PMID 35538152, 2022).
cancer (24 papers, 2014 to 2026). A tumor composed of atypical neoplastic, often pleomorphic cells that invade other tissues. "Beyond cancer, RBMS1 has been associated with cardiovascular disease, potentially contributing to coronary heart disease through its involvement in lipid metabolism and inflammatory pathways." (PMID 41596407, 2026). "Dysregulation of RBMS1 has been implicated in oncogenesis, with aberrant expression patterns linked to tumor progression and metastasis across multiple cancer types." (PMID 41596407, 2026). "Multiple studies have shown that RBMS1 expression is altered in several types of cancer, and its dysregulation has been associated with tumor progression and metastasis." (PMID 37511060, 2023). "Our study revealed that RBMS1 has a higher mutation rate in GC than most cancers." (PMID 35910231, 2022). "The RBMS1 gene encodes a member of a small family of proteins that have been implicated in diverse functions, such as DNA replication, gene transcription, cell cycle progression, and apoptosis coordinated by c-Myc, a major proto-oncogene in human cancer." (PMID 35361764, 2022). "RBMS1 has been reported to be involved in regulating mRNA stability and translation 49, 50, making it a potential therapeutic target in cancer treatment." (PMID 40963905, 2025). "Depletion of RBMS1 suppresses cancer cell migration and invasion in vitro and inhibits cancer cell metastasis in vivo." (PMID 38342601, 2024). "RBMS1 has been extensively studied for its role in cancer and found to regulate various cellular processes such as alternative splicing, mRNA stability, and translation, making it a potential therapeutic target for cancer treatment." (PMID 37511060, 2023). "Expression of miR-4442 in cancer tissue was negatively correlated with the expression of RBMS1 mRNA in cancer tissue, with a correlation coefficient (ρ) of −0.342." (PMID 37510319, 2023). "In this study, we found that RBMS1 predicts poor clinical outcomes in GC based on publicly available databases and GC tissue samples from our clinical cancer center." (PMID 35361764, 2022). "For instance, RBMS1 has been reported to regulate cancer progression through modulating the stability and translation of target mRNAs." (PMID 35538152, 2022). "In this study, we report the DNA sequence recognition mechanism of a regulatory protein RBMS1 that stringently regulates proto-oncogene c-myc levels and presents the future for developing efficient cancer targeted gene therapy against c-myc proto-oncogene." (PMID 33999211, 2021). "It is noteworthy that whether RBMS1 broadly regulates the biogenesis of other circRNAs and its functional role in different cancer types remains to be further explored." (PMID 40963905, 2025). "The present study suggests that miR-4442 regulates cell proliferation, migration, and invasion in CRC cells, which could be explained by inhibiting the function of one of its target genes, the cancer-suppressor gene RBMS1." (PMID 37510319, 2023). "However, we found that RBMS1 expression was dramatically decreased in HCC tissues in contrast to adjacent normal samples and forced RBMS1 expression curbed HCC cancer cell proliferation in vitro and in vivo." (PMID 36989117, 2023). "Additionally, RBMS1 expression levels have been shown to correlate with cancer progression and patient survival in certain types of cancer." (PMID 37511060, 2023). "We also confirmed that RBMS1 expression was obviously increased in GC tissues compared with corresponding adjacent noncancerous tissues by IHC staining based on GC patient tissues collected from our clinical cancer center." (PMID 35361764, 2022). "This suggests that RBMS1 may have a broad effect on PD-L1 across different types of cancer." (PMID 37628671, 2023).
cancer (continued). "Hence, our study reveals a novel molecular mechanism for regulating PD-L1 levels by an RNA-binding protein, which has the potential for developing combinatorial cancer immunotherapies against human TNBC by combining RBMS1 depletion with CTLA4 immune checkpoint blockade or CAR-T therapy." (PMID 35538152, 2022). "Consistently, depletion of RBMS1 in MDA-MB-231, BT-549, and HCC1937 cells enhanced the T cell-mediated cancer cell killing in vitro." (PMID 35538152, 2022). "Cells positively expressing RBMS1 were identified by the presence of brown–yellow particles distributed in the cytoplasm in carcinoma tissue but not in adjacent nonmalignant tissues." (PMID 35361764, 2022).
cardiovascular disease (2 papers, 2020 to 2025). "For example, its linear isoform can regulate the c-myc-enhancer-binding factor RBMS1, while its circular isoform is confirmed to be an important AS regulator that causes skipping of exons and are mainly found in cardiovascular disease." (PMID 32760422, 2020).
RBMS1 also shares sentences with these, for which no sentence is quoted: hepatocellular carcinoma (4 papers); ischemia (2); ischemic stroke (2); pancreatic cancer (2); Stroke (2); thalassemia (2); Alzheimer disease (1); atherosclerosis (1); bacterial infection (1); breast disease (1); Cerebral ischemia (1); dilated cardiomyopathy (1); hemorrhagic stroke (1); Hepatic fibrosis (1); Hypertension (1); hypertrophy (1); injury (1); Intellectual disability (1); liver disease (1); lung adenocarcinoma (1); lymph node metastasis (1); metabolic disorders (1); multiple sclerosis (1); non-small cell lung carcinoma (1); oral cancer (1); pancreatic ductal adenocarcinoma (1); peritoneal adhesions (1); pulmonary arterial hypertension (1); renal carcinoma (1); respiratory diseases (1).
A further 3 diseases each share a sentence with RBMS1 in 1 paper.